RNU6-996P (RNA, U6 small nuclear 996, pseudogene)
Gene: Small nuclear RNA gene on chromosome 9 (107,663,140 to 107,663,246, reverse strand). Ensembl gene ENSG00000202308.
Homologues: Orthologues: chimpanzee U6 (98% identical), macaque U6 (96% identical), pig U6 (84% identical). Paralogues in human: RNU6-1011P (87% identical), RNU6-1029P (87% identical), RNU6-12P (87% identical), RNU6-13P (87% identical), RNU6-16P (87% identical), RNU6-25P (87% identical), RNU6-29P (87% identical), RNU6-32P (87% identical), RNU6-33P (87% identical), RNU6-36P (87% identical), RNU6-38P (87% identical), RNU6-41P (87% identical), and 1290 more.